CD164 (CD164 molecule)
Description:
Sialomucin that may play a key role in hematopoiesis by facilitating the adhesion of CD34(+) cells to the stroma and by negatively regulating CD34(+)CD38(lo/-) cell proliferation. Modulates the migration of umbilical cord blood CD133+ cells and this is mediated through the CXCL12/CXCR4 axis. May play an important role in prostate cancer metastasis and the infiltration of bone marrow by cancer cells. Promotes myogenesis by enhancing CXCR4-dependent cell motility. Positively regulates myoblast migration and promotes myoblast fusion into myotubes (By similarity).
Synonyms: MUC-24; MGC-24; MGC-24v; DFNA66; endolyn
Tractability: Antibody: UniProt places it where antibodies can reach, with high confidence; its Gene Ontology location is reachable by antibodies, with high confidence; UniProt predicts a signal peptide or a membrane-spanning region. PROTAC: ubiquitination databases record sites on it.
Gene: Protein-coding gene on chromosome 6 (109,366,514 to 109,382,469, reverse strand). Ensembl gene ENSG00000135535.
Subcellular location: Lysosome membrane; Endosome membrane; Cell membrane; Secreted (Isoform 2)
Gene Ontology:
Molecular function: protein binding
Biological process: cell adhesion; heterophilic cell-cell adhesion; hemopoiesis; immune response; negative regulation of cell adhesion; signal transduction
Cellular component: endosome; lysosome; plasma membrane; cytoplasmic vesicle; endosome membrane; extracellular region; lysosomal membrane
Genetic constraint (gnomAD): Loss-of-function variants: 6 observed, 9.6 expected, observed/expected ratio (o/e) 0.62, 90% interval 0.34 to 1.23. That is too few expected variants to judge how well the gene tolerates losing a copy. Missense variants: 214 observed, 157.82 expected, observed/expected ratio (o/e) 1.36, 90% interval 1.21 to 1.52. Synonymous variants: 102 observed, 65.97 expected, observed/expected ratio (o/e) 1.55, 90% interval 1.32 to 1.82.
Gene-disease validity (ClinGen):
ClinGen rates the evidence that CD164 causes each of these diseases.
autosomal dominant nonsyndromic hearing loss (autosomal dominant): Moderate. Autosomal dominant form of nonsyndromic deafness.
Homologues: Orthologues: chimpanzee CD164 (99% identical), macaque CD164 (92% identical), rabbit CD164 (69% identical), pig CD164 (68% identical), guinea pig CD164 (65% identical), dog CD164 (63% identical), mouse Cd164 (62% identical), rat Cd164 (60% identical), tropical clawed frog cd164 (39% identical), zebrafish cd164 (34% identical), Drosophila melanogaster vsg (22% identical). Paralogues in human: CD164L2 (25% identical), TMEM123 (23% identical).
Diseases named in the same sentence as CD164 in open-access papers:
CD164 is named in the same sentence as 48 diseases in open-access papers, as found by Europe PMC text mining. Sharing a sentence is not in itself a finding about the gene and the disease. The quoted sentences say what the papers report.
colon cancer (8 papers, 2013 to 2025). "Highly expressed in colon cancer, CD164 drives proliferation and metastases along the CXCL12 (SDF-1)/CXCR4 signaling axis." (PMID 40692786, 2025). "It is also shown that inhibition of CD164 expression in colon cancer cell line HCT116 reduces cancer cell proliferation, mobility, and metastasis in vitro and in vivo." (PMID 32364222, 2020). "For example, CD164 is highly expressed in colon cancer, where it promotes proliferation and metastasis by regulating signaling through the CXCL12 (SDF-1) receptor CXCR4." (PMID 31007847, 2019). "Previous studies have demonstrated the inhibition of cell proliferation by CD164 knock-down in colon cancer cells." (PMID 24094005, 2013). "Additionally, greatly overexpressed in many malignancies, including glioma, prostate cancer, colon cancer, and bladder cancer, is CD164." (PMID 40692786, 2025). "The study suggested that lncRNA RP11-619L19.2 could promote colon cancer development by regulating the miR-1271-5p/CD164 axis." (PMID 34692670, 2021). "However, over the years evidence has shown that CD164 can promote tumorigenesis, invasion, and metastasis in lymphoma, prostate cancer, colon cancer, ovary cancer, lung cancer and brain cancer." (PMID 31007847, 2019). "Besides, our results reveal that DNA methylation could cause CD164 overexpression in the early stage of PTC, and it has been reported that CD164 could promote the proliferation and metastasis of colon cancer cells in vivo and vitro through the CXCR4 pathway." (PMID 31126066, 2019). "For example, RP11-619L19.2 regulates the expression of CD164 and EMT through sponge adsorption of miR-1271-5p, and promotes the development of colon cancer." (PMID 34345216, 2021).
prostate carcinoma (5 papers, 2006 to 2019). A carcinoma that arises from epithelial cells of the prostate gland. "Lnc-CD164L2 has a gene locus resides in the intronic region of the protein coding gene CD164, which has been found to act as a metastasis promoter in prostate cancer." (PMID 29416609, 2018). "SDF-1α also enhances the expression of CD164 mRNA and alters the expression of the CD164 protein in prostate cancer cell lines." (PMID 24094005, 2013). "Using monoclonal antibodies, we determined that the neutralization of CD164 with antibodies blocked the adhesion of prostate cancer cells to human bone marrow endothelial cells and inhibited subsequent invasion." (PMID 16859559, 2006). "The findings presented in this report suggest that CD164 participates in the initial 'locking' of prostate cancer cells to the endothelium and thereby facilitates the invasion of tissue." (PMID 16859559, 2006). "To determine at which stage CD164 is expressed during the progression of prostate cancer, we used an immunohistochemical analysis of clinical specimens of prostate cancer tumors." (PMID 16859559, 2006). "We present data that demonstrate that CD164 mRNA and protein is expressed by prostate cancer cell lines which are responsive to CXCL12 stimulation." (PMID 16859559, 2006). "Functional studies demonstrated that blocking CD164 on prostate cancer cell lines reduced the ability of these cells to adhere to human bone marrow endothelial cells, and invade into extracellular matrices." (PMID 16859559, 2006). "Initial localization of cancer cells (including prostate cancer cells) to the endothelium appears to be mediated largely by lectins and mucins such as CD164." (PMID 16859559, 2006). "Using prostate cancer tissue microarrays, it was noted that the staining intensity for CD164 correlated with increased prostate-specific antigen (PSA) expression." (PMID 16859559, 2006). "Staining of microarrays with CD164 monoclonal antibodies revealed that CD164 protein expression was localized to the cytoplasm and that the level of expression ranged from moderate to high in clinically benign and localized prostate cancer tumors." (PMID 16859559, 2006). "In summary, we demonstrated that full-length CD164 is expressed by human prostate cancer cell lines and human prostate cancer tumors." (PMID 16859559, 2006). "If CD164 does regulate the growth of prostate cancer cells, this would be a particularly attractive therapeutic target for two reasons." (PMID 16859559, 2006). "Collectively, our data suggest that CD164 plays an important role in prostate cancer metastasis and the infiltration of bone marrow by cancer cells." (PMID 16859559, 2006). "Functionally, antibody blocking of CD164 prevents the binding and migration of prostate cancer cells to bone marrow endothelium and invasion via the extracellular matrix." (PMID 16859559, 2006). "In this report, we demonstrate that the full-length CD164 is expressed by human prostate cancer cell lines under basal conditions." (PMID 16859559, 2006). "Furthermore, CD164 serves as a factor in the regulation of prostate cancer cell adhesion to the human bone marrow endothelial monolayer." (PMID 24094005, 2013). "Importantly, CD164 is expressed in human prostate cancer tissues paralleling the PSA expression, and negatively correlating with AR expression." (PMID 16859559, 2006). "At present, we are in the process of evaluating whether CD164 plays a similar role in prostate cancer cells." (PMID 16859559, 2006). "Our findings suggest that CD164 may participate in the localization of prostate cancer cells to the marrow and is further evidence that tumor metastasis and hematopoietic stem cell trafficking may involve similar processes." (PMID 16859559, 2006). "First, because CXCL12 up regulates CD164 expression and stimulates prostate cancer cell proliferation and adhesion, therapies designed to disrupt CD164 or the CXCL12/CXCR4 axis could be used to alter tumor progression via several mechanisms." (PMID 16859559, 2006).
prostate carcinoma (continued). "Our experiments revealed that antibodies that recognize CD164 inhibited the binding of prostate cancer cells to human bone marrow endothelium and reduced invasion of the extracellular matrix by prostate cancer cells, irrespective of whether the cancer cells were stimulated by exposure to CXCL12." (PMID 16859559, 2006). "The results of this study suggest that CD164 may play a central role in prostate cancer metastasis." (PMID 16859559, 2006). "In prostate cancer, CXCL12/CXCR4 signaling induces the expression of CD164 and promotes homing of cancer cells to the bone marrow." (PMID 31007847, 2019). "In prostate carcinomas, not only the HIF-1α/AP-1 complex but also intracellular Zn2+ are involved in the induction of CD164 gene expression." (PMID 24094005, 2013). "While screening prostate cancers for CXCL12-responsive adhesion molecules, we identified CD164 (MGC-24) as a potential regulator of homing." (PMID 16859559, 2006). "CXCL12 enhanced the binding of prostate cancer cells to bone marrow endothelial cells, and CXCL12 up regulated the expression of CD164 mRNA and protein." (PMID 16859559, 2006). "Using prostate cancer cell lines, it was demonstrated that CXCL12 induced both the expression of CD164 mRNA and protein." (PMID 16859559, 2006). "All of the prostate cancer cells expressed mRNA coding for the full length CD164, and none of the alternatively spliced forms were observed." (PMID 16859559, 2006).
glioma (4 papers, 2018 to 2025). A benign or malignant brain and spinal cord tumor that arises from glial cells (astrocytes, oligodendrocytes, ependymal cells). "The present study was designed to determine the potential association between CD164 and glioma type and grade, and to investigate the effects and underlying molecular mechanisms of CD164 depletion on the proliferation, migration, and invasion of GBM cells." (PMID 31007847, 2019). "By means of the PTEN/PI3K/AKT pathway, CD164 knockdown reduces cell proliferation and generates death in gliomas." (PMID 40692786, 2025). "Tissue microarray analyses showed that CD164 expression positively correlated with glioma type and grade." (PMID 31007847, 2019). "CD164 was highly expressed in the cytoplasm and membrane of glioma cells, although heterogeneous staining patterns were observed across glioma samples." (PMID 31007847, 2019). "On the other hand, CD164 downregulation reduces glioma cell proliferation, migration, and tumor invasion via depression of the Akt/mTOR pathway and autophagy induction." (PMID 31387280, 2019). "Grade III and IV gliomas presented with significantly higher mean CD164 H-scores than both grade II gliomas and normal brain tissue." (PMID 31007847, 2019). "CD164 mRNA expression correlated with worse overall survival in two PRECOG glioma (HR = 2.02, 95% CI 1.56–2.63; HR = 2.13, 95% CI 1.03–4.42) and one astrocytoma (HR = 1.70, 95% CI 1.02–2.81) datasets." (PMID 31007847, 2019). "The present study systematically evaluated CD164 expression in clinical glioma specimens and the effects of CD164 silencing on cultured glioblastoma cells." (PMID 31007847, 2019). "CD164 mRNA expression was significantly higher in grade IV glioma (p < 0.001) than in lower glioma grades." (PMID 31007847, 2019). "Using tissue microarray immunohistochemistry, we show that there is a significant correlation between CD164 expression and glioma type and grade." (PMID 31007847, 2019). "In conclusion, both tissue microarray immunochemistry and gene expression analyses confirmed a positive relationship between CD164 expression and glioma histological grade." (PMID 31007847, 2019). "In gliomas, knockdown of CD164 inhibited cell proliferation and promoted apoptosis through the PTEN/PI3K/AKT pathway." (PMID 31007847, 2019). "In conclusion, our study suggests that overexpression of CD164 in glioma cells may contribute to tumor growth through enhanced autophagy." (PMID 31007847, 2019). "In detail, CD164 is a member of sialomucin family, which plays a role in proliferation, adhesion, and differentiation of hematopoietic stem cells and different types of tumors, including gliomas." (PMID 31387280, 2019). "In addition, we analyzed CD164 mRNA expression in human glioma specimens by accessing a Gene Expression Omnibus (GEO) dataset." (PMID 31007847, 2019). "Further evidence for the adverse impact of CD164 expression on GBM progression was found upon analysis of astrocytoma/glioma PRECOG datasets, which showed a significant, inverse correlation between CD164 levels and survival rates." (PMID 31007847, 2019). "Interestingly, a previous study found that downregulation of CD164 by short hairpin RNA inhibited cell proliferation and promoted apoptosis in human U87MG glioma cells both in vitro and in vivo via the PTEN/PI3K/Akt signaling pathway." (PMID 31007847, 2019).
medulloblastoma (4 papers, 2018 to 2025). A malignant, invasive embryonal neoplasm arising from the cerebellum. "A previous study has shown that miR-219 inhibits the proliferation, migration and invasion of medulloblastoma cells by targeting CD164." (PMID 32364222, 2020). "MiR-219 also directly targets CD164 to stop invasion and proliferation in medulloblastoma." (PMID 40692786, 2025). "In medulloblastoma, miR-219 downregulated CD164 and in consequence MYC was degraded." (PMID 30038718, 2018).
ovarian cancer (4 papers, 2013 to 2020). A primary or metastatic malignant neoplasm involving the ovary. "To determine the association between the abundance of the CD164 protein and ovarian cancer, we used a tissue microarray containing normal ovarian tissue, benign tumor tissue and different stages of malignant tumors for immunohistochemical staining." (PMID 24094005, 2013). "A tumorigenic role of CD164 has been demonstrated in ovarian cancer where CD164 is upregulated in malignant ovarian cancer cell lines." (PMID 32719743, 2020). "In this study, the CD164 expression profiles of ovarian cancer cells were measured and were suggested to have a correlation with ovarian tumorigenesis processes, including proliferation, migration and invasion." (PMID 24094005, 2013). "Our data demonstrated that higher expression levels of CD164 were identified in malignant ovarian cancer cell lines, such as SKOV3 and HeyA8." (PMID 24094005, 2013). "Our findings suggest that the increased expression of CD164 is involved in ovarian cancer progression via the SDF-1α/CXCR4 axis, which promotes tumorigenicity." (PMID 24094005, 2013). "The clinicopathological correlation of ovarian cancer with CD164 was assessed in a 97-patient tumor tissue microarray." (PMID 24094005, 2013). "In ovarian cancer cells, CD164 was localized in the cytosol and nucleus suggesting that nuclear CD164 might regulate CXCR4 promoter activity." (PMID 32719743, 2020). "Furthermore, tissues from different stages of ovarian cancers were stained to determine the amount of CD164 protein (+1 faint, +2 moderate, +3 strong and +4 very strong)." (PMID 24094005, 2013). "To address whether CD164 is involved in ovarian tumorigenesis, we measured the expression of CD164 in some ovarian cancer cell lines and the normal ovarian cell line, hOSE, by immunoblotting analysis." (PMID 24094005, 2013). "Thus, targeting CD164 may serve as a potential ovarian cancer biomarker, and targeting CD164 may serve as a therapeutic modality in the management of high-grade ovarian tumors." (PMID 24094005, 2013). "Hence, the expression level of the CD164 protein could be used as a prognostic marker for ovarian cancer." (PMID 24094005, 2013). "We also confirmed that CD164 had the ability to increase the CXCR4 and CXCR7 mRNA levels in some ovarian cancer cells." (PMID 24094005, 2013).
bladder cancer (3 papers, 2018 to 2022). "High level of CD164 was related to the distant metastasis and vascular invasion of bladder cancer patients." (PMID 30022623, 2018). "Silencing of CD164 could inhibit the progression of tumors in vivo and in vitro, which may become an effective target in the treatment of bladder cancer." (PMID 30022623, 2018). "CD164 could promote tumor progression and predict the poor prognosis of bladder cancer." (PMID 32364222, 2020). "Therefore, we speculated that CD164 possibly played roles in bladder cancer through regulating the expression of CXCR4 and relevant pathways." (PMID 30022623, 2018). "But the roles of CD164 in human bladder cancer have not yet been studied." (PMID 30022623, 2018).